IL6 (interleukin 6)
Diseases named in the same sentence as IL6 in open-access papers (continued):
Sharing a sentence is not in itself a finding about the gene and the disease.
non-small cell lung carcinoma (141 papers, 1996 to 2026). A group of at least three distinct histological types of lung cancer, including non-small cell squamous cell carcinoma, adenocarcinoma, and large cell carcinoma. "The main idea of this research was to disclose the linkage between both IL-6 rs1800795 and IL-1β rs16944 variants and susceptibility to non-small-cell lung cancer (NSCLC) in Egyptians." (PMID 38103126, 2024). "Preclinical evidence suggests the feedforward cytokine loop of interleukin-6/Janus kinases (JAK)/STAT3 plays a role in epidermal growth factor receptor tyrosine kinase inhibitor (EGFR TKI) resistance in EGFR-mutated non-small cell lung cancer (NSCLC)." (PMID 34773474, 2022). "IL-6-174G/C polymorphism has a close association with cancer pain of patients with non-small cell lung cancer." (PMID 31970102, 2019). "Anti-IL-6 antibody treatment in late-stage cachexia has been unsuccessful in clinical trials involving participants with non-small-cell lung cancer, and the pleiotropic effects of IL-6 might lead to side effects such as an increased risk of infections." (PMID 40275022, 2025). "IL6 has been associated with poor prognosis in non-small-cell lung cancer patients." (PMID 39335552, 2024). "IL-6 polymorphism was associated with survival prognosis of non-small-cell lung cancer (nSCLC)." (PMID 35692583, 2022). "Additionally, ALD518, a humanized IL-6 antibody used as a IL-6 antagonist, has been demonstrated during a Phase II clinical trial in non-small-cell-lung-cancer patients a deceleration in lean body mass loss." (PMID 35457471, 2022). "One study demonstrated that the loss of TIMP3 expression might increase IL-6 production via the tumor necrosis factor α/nuclear factor κB pathway in patients with HPV-infected non-small cell lung cancer." (PMID 29731768, 2018). "Therapeutic agents targeting the IL-6/STAT3 pathway have shown promise in the treatment of non-small cell lung cancer and are poised to emerge as efficacious interventions in this domain." (PMID 40426998, 2025). "IL-6, which helps regulate inflammation, plays a significant role in the development and progression of non-small cell lung cancer." (PMID 41376623, 2025). "Non-small cell lung cancer (NSCLC) is primarily driven by IL-6, while pancreatic tumors predominantly release IL-8 and IL-1." (PMID 41514616, 2025). "Previous literature has shown that IL-37 inhibits invasion and metastasis in non-small cell lung cancer by suppressing the IL-6/STAT3 signaling pathway." (PMID 40444012, 2025). "Studies have shown that patients with high baseline plasma IL-6 levels have a worse response in patients with advanced non-small cell lung cancer and liver cancer treated with PD-1/PD-L1 inhibitors." (PMID 40433391, 2025). "For example, activation of Akt1 increased the expression of IL-6, thereby promoting the phosphorylation and activation of Stat3 in non-small cell lung cancer (NSCLC) cells." (PMID 41415834, 2025). "PCA has previously been proven to decrease the expression of NF-κB in non-small-cell lung cancer (NSCLC) cell lines, A549, H3255, and Calu-6 cell lines, and the decreased NF-κB expression was associated with a reduction in IL-6." (PMID 40362355, 2025). "PDGFR-beta, IL-6, IL-1, non-small cell lung cancer, and TGF-beta signaling pathways were the most enriched." (PMID 38891028, 2024). "A self-stimulatory role for IL-6 has been shown for instance for fibroblasts in vocal fold leukoplakia and for non-small cell lung carcinoma (NSCLC)." (PMID 38422751, 2024). "In patients with non-small cell lung cancer, a lower level of baseline IL6 determines the response towards the PD1/PDL1 inhibition, suggesting that combining the two therapies will improve the effectiveness of fighting cancer." (PMID 39766086, 2024). "It has been reported that the increased secretion of IL-6 can induce resistance in non-small cell lung cancer cells to osimertinib, a third-generation EGFR-TKI." (PMID 37404767, 2023).
non-small cell lung carcinoma (continued). "Most of the hub genes in the network like GAPDH, IL6, CDK1, PTEN, etc. are either associated with non-small cell lung cancer itself or other forms of cancers." (PMID 35330393, 2022). "The level of serum IL-6 in patients with non-small cell lung cancer (NSCLC) decreases significantly after chemotherapy, which is related to reducing cancer recurrence and prolonging survival." (PMID 36591515, 2022). "Previous studies indicated that increased interleukin (IL)-6 was related to poor PFS in non-small cell lung carcinoma patients treated with anti-PD-1 inhibitors." (PMID 35874780, 2022). "Studies have demonstrated that a high level of circulating IL-6 is correlated with adverse prognosis of various cancer types including non-small cell lung cancer (NSCLC)." (PMID 36275807, 2022). "By boosting interleukin-6 (IL-6) production in gefitinib-resistant non-small cell lung cancer cells, highly expressed LINC00460 acts as a competitive bait for mir-149-5p." (PMID 35897925, 2022). "In non-small cell lung cancer, estradiol upregulates the expression of IL-6 under the mediation of ERβ." (PMID 35292057, 2022). "Previous studies determined that IL-6 promotes metastasis of non-small-cell lung cancer via the NF-κB pathway." (PMID 34966411, 2021). "A recent study reported that IL-6 can induce EMT of non-small cell lung cancer cells by STAT3 activation and insulin-like growth factor-1 receptor (IGR-1R)." (PMID 34064322, 2021). "Interleukin-6 was identified as an important factor in hypoxia- and aldehyde dehydrogenase-based gefitinib adaptive resistance in non-small cell lung cancer cells." (PMID 32923394, 2020). "CAFs produced also IL-6, which further promoted EMT in cancer cells in collaboration with TGF-β1 and the analysis on human non-small cell lung cancer tissues unraveled that IL-6 expression in CAFs was an independent prognostic factor." (PMID 33050237, 2020). "In our previous study, HIC1 was found to be a suppressor of IL-6 in non-small cell lung cancer, and HIC1 was found to be weakly expressed in the TNBC cell line MDA-MB-231." (PMID 31795965, 2019). "Downregulation of IL-6/JAK/STAT3 pathway activation subsequently reduces the expression of PD-L1 in non-small cell lung cancer." (PMID 31533774, 2019). "The EGFR signaling pathway can also regulate PD-L1 expression through the IL-6/JAK/STAT3 pathway in non-small cell lung cancer (NSCLC) cells." (PMID 31480382, 2019). "In other study, IL-6 was important for the processing that IL-17 enhanced the invasion of non-small cell lung cancer." (PMID 31796027, 2019). "In non-small cell lung cancer, Nox4 expression is positively correlated with IL-6 expression and exogenous IL-6 treatment significantly enhances Nox4 signaling." (PMID 30513726, 2018). "Most SCCHN and non-small cell lung cancer (NSCLC) cell lines secrete IL-6 and express receptors for IL-6." (PMID 21559372, 2011). "Interleukin-6 is an important independent mediator of elevated C-reactive protein concentrations in patients with non-small-cell lung cancer." (PMID 15570310, 2004). "The inhibition of the IL6/IL8 - JAK2 signaling can eliminate BRD4 phosphorylation and restore the sensitivity of tumors to BET inhibitors.In KRAS - mutated tumors, including non - small - cell lung cancer (NSCLC), an up - regulation of BCL6 has been observed." (PMID 39838405, 2025). "Notably, some trials has recently shown changes in some cytokines, like IL-6 in the blood of patients treated with ICIs, correlating theme with anticancer response and cardiovascular effects in patients with non small cell lung cancer." (PMID 38322766, 2024). "Decreased cancer cell proliferative activity has been shown in non-small cell lung cancer and breast cancer when anti-IL6 antibodies were combined with EGFR small molecule inhibitor Erlotinib and anti-Human Epidermal Growth Factor Receptor (HER2) monoclonal antibody Trastuzumab, respectively." (PMID 39766086, 2024).
non-small cell lung carcinoma (continued). "In addition to promoting the EC cell growth, IL-6 is upregulated in EGFR-mutant non-small cell lung cancer, where it suppresses T- and NK-cell functions." (PMID 38464838, 2024). "Finally, non-small cell lung carcinoma (NSCLC) is less sensitive to cisplatin when IL-6 produced by CAFs stimulates well-studied pro-survival signalling cascades and enhances TGF-β1-driven EMT in lung cancer cells." (PMID 36555218, 2022). "SB-203580 is a p38 MAPK-specific inhibitor that could suppress IL-6-stimulated non-small cell lung cancer cells proliferation by inhibiting IL-6-induced p38 MAPK phosphorylating activity." (PMID 34721037, 2021). "However, increasing evidence suggested that T-cell immunoglobulin domain and mucin domain 4 (TIM4) and NF-kB are involved in the tumor progression induced by IL-6 in non-small cell lung cancer." (PMID 34657635, 2021). "High circulating levels of IL-6 have been reported in patients with different types of cancers such as breast, colorectal, ovarian, renal, non-small-cell lung cancer (NSCLC), and head and neck, and circulating IL-6 levels are reported to be increased in patients with recurrent tumors." (PMID 34834397, 2021). "In non-small cell lung cancer (NSCLC), secretion of oncostatin-M (OSM), a member of the IL-6 cytokine family, by cancer-associated fibroblasts increases STAT3 activity through activation of JAK1 and is a possible mechanism of resistance to targeted therapy such as EGFR and MEK inhibitors." (PMID 33521321, 2020). "However, a recent paper has demonstrated TIMP-1 mediated chemoresistance in a non-small cell lung carcinoma model via induction of IL-6 secretion." (PMID 33023532, 2020). "Similarly, an aglycosylated mAb (ALD518; Alder) targeting IL-6 is being tested in phase-2 for a variety of diseases including rheumatoid arthritis, non-small cell lung cancer (NSCLC), and oral mucositis." (PMID 28018347, 2016). "Markers of the inflammatory response, interleukin 6, C-reactive protein, albumin and full blood count, were measured in non-small-cell lung cancer (NSCLC) patients (n = 21) with and without weight loss ( > 5%)." (PMID 8664130, 1996). "Also, IL-6 produced from CAFs may develop resistance to cisplatin in non-small cell lung cancer (NSCLC) through promoting EMT." (PMID 38244071, 2024). "Similarly, other studies have shown that, at least in non-small cell lung carcinoma, increased IL-6 production (which is also upregulated in vMyx-hTNF/PBMC-treated animals) after anti-PD-L1/anti-PD-1 therapy was a potential predictor of positive outcome in patients." (PMID 34553039, 2021). "There is evidence for IL-6 in the relationship with colorectal cancer and tumour necrosis and also it has been found that IL-17 might be a pivotal cytokine involved in tumor progression of non-small cell lung cancer (NSCLC)." (PMID 28448466, 2017). "Since intratumoral expression of MIF was correlated with serum IL-6 in patients with non-small cell lung cancer and IL-6 was shown to be one of the potential MIF-regulated genes in DU145 cells, we speculate that NPRA signaling may regulate IL-6 in PCa cells via MIF." (PMID 21586128, 2011). "It is noteworthy that the latest report has revealed that FXR promotes non-small-cell lung cancer metastasis by activating the Jak2/STAT3 signaling pathway through the transactivation of the IL6ST and IL6 genes." (PMID 39940889, 2025). "TAMs secrete PD-L1 and the IL-6 generated by TAMs fosters P-STAT3 in non-small cell lung cancer and therefore honed PD-L1 in non-small cell lung cancer." (PMID 39189933, 2024). "For instance, BAs activate the FXR receptor, thereby promoting the metastasis of non-small cell lung cancer (NSCLC) by mediating the JAK2/STAT3 signaling pathway through the transactivation of IL-6ST and IL-6 genes." (PMID 39769418, 2024).
non-small cell lung carcinoma (continued). "According to findings of other studies, IL-6 produced by TAM promoted the occurrence of hepatic cancer through STAT3 signaling pathway, while IL-10 produced by TAM promoted the occurrence of non-small cell lung cancer through STATI pathway." (PMID 38244580, 2024). "TMQ showed superior therapeutic effects to TM in non-small cell lung cancer, including an increased splenic index, IFN-γ, ROS, and MDA levels, and decreased TNF-α and IL-6 levels." (PMID 39508039, 2024). "Blocking IL-6/STAT3 signal transduction can significantly inhibit tumor growth and STAT3 phosphorylation in mice xenografts with non-small cell lung cancer." (PMID 36990991, 2023). "In such studies, survivors of childhood ALL exhibiting poor sleep were found to have elevated plasma levels of IL-6, IL1b and CRP, and elevated IL-6 levels were correlated to poor sleep in non-small cell lung cancer patients receiving chemoradiotherapy." (PMID 36213755, 2022). "A study conducted in patients with non-small cell lung cancer (NSCLC) and muscle atrophy pointed out that the overexpression of IL-6 and IL-8 can be potentially used as biomarkers of a poor prognosis in patients with NSCLC." (PMID 34552592, 2021). "In non-small-cell lung cancer (NSCLC) and HCC, IL-6 produced by TAMs supported the expansion and drug resistance of CSCs in a STA3-dependent manner." (PMID 32397392, 2020). "Here we found that CBP501 inhibits migration of non-small cell lung cancer (NSCLC) cells in vitro, even in the presence of migration inducing factors such as WNT, IL-6, and several growth factors." (PMID 29088764, 2017). "Here we report that the PI3K/Akt1/IL-6/STAT3 signalling pathway regulates generation and stem cell-like properties of Non-Small Cell Lung Cancer (NSCLC) tumor initiating cells (TICs)." (PMID 26486080, 2015). "Similar to the IL-6/STAT3 pathway, IL-6 was shown to upregulate the expression of lncRNA ZEB2-AS1 through STAT1 pathway, which fostered the proliferation and migration of non-small cell lung cancer cells." (PMID 35842651, 2022). "Gefitinib (Iressa) is an inhibitor of EGFR-tyrosine kinase that inhibits EGFR-dependent but not IL-6-dependent phosphorylation of STAT3, and is clinically used to treat non-small cell lung cancer patients with EGFR-activating mutations." (PMID 33392396, 2021). "We examined IL-6 effects on growth, epithelial-mesenchymal transition (EMT) process, and metastatic ability of CD133+ and CD133– cell subpopulations isolated from three non-small cell lung cancer (NSCLC) cell lines: A549, H157, and H1299." (PMID 26675547, 2016). "Interestingly, despite the high levels of plasma TNFα and IL-6 in patients with non-small cell lung cancer compared with healthy volunteers, the difference in plasma TNFα and IL-6 between cachectic and non-cachectic patients is not significant." (PMID 24787299, 2014). "A previous study reported that quercetin could downregulate IL-6, STAT-3, Bcl2 activity, NF-kB expression, and upregulate the Annexin and the PI cell population through induction of mitochondrial-mediated apoptosis in A549 cells in non-small-cell lung cancer (NSCLC)." (PMID 36926328, 2023).
bladder cancer (138 papers, 1997 to 2026). "The mean IL-6 level in patients was nearly 2.5 times higher than in controls, indicating a robust inflammatory response associated with the presence of bladder cancer, which makes IL-6 a strong candidate as both a prognostic marker and a therapeutic target." (PMID 41614883, 2025). "Here, the authors show in several preclinical models that targeting IL6/JAK/STAT3 molecular pathway is a potential therapeutic approach for SMARCB1-deficient bladder cancer." (PMID 38355560, 2024). "Specifically, the panel of Actinomycetaceae + Arachidonic acid + IL-6 showed promise as noninvasive screening and diagnostic tools for bladder cancer." (PMID 38970045, 2024). "Particularly, the proinflammatory cytokine IL-6 was reported to be associated with initiation and progression of bladder cancer." (PMID 38970045, 2024). "Previous studies have focused on determining the relationship between the IL-6-174G/C polymorphism (rs1800795) and bladder cancer." (PMID 37047238, 2023). "Cancer-associated fibroblasts secreted IL-6, which activated its receptor on bladder cancer cells, subsequently leading to the increased phosphorylation of STAT3 and providing IL-6-activated EMT programming." (PMID 36230984, 2022). "High IL6 expression in bladder cancer samples has also been associated with advanced stages, higher post-treatment recurrence rate, and decreased survival rate." (PMID 33244139, 2020). "We also observed that IL6 expression is up-regulated in aggressive bladder cancer tissues, correlates with CAF marker ACTA2 and is associated with a poor prognosis." (PMID 30744595, 2019). "In bladder cancer, clinical findings showed that patients have higher serum IL-6 levels than the healthy controls and that higher IL-6 levels are associated with poorer prognosis." (PMID 30744595, 2019). "To explore the underlying molecular mechanism of miR-153 in bladder cancer, we measured interleukin-6 (IL6) expression in supernatants of miR-153-overexpressing or IDO1 knocked down bladder cancer cells compared to the negative control cells." (PMID 31355138, 2019). "Studies have suggested that IL6 is associated with a number of biological functions in bladder cancer, including cell proliferation, cell transformation, inflammation, and detrusor smooth muscle contractility." (PMID 23762858, 2013). "Treatment with interleukin-6 (IL-6) was associated with anti-tumor effect via the induction of apoptosis in mouse bladder carcinoma." (PMID 22962576, 2012). "We assessed the effects on three biomarkers previously reported to be associated with bladder cancer i.e., interleukin- 6 (IL-6), IL-8 and vascular endothelial growth factor (VEGF)." (PMID 23300915, 2012). "Additionally, the study revealed a correlation between elevated IL-6 expression and more aggressive forms of bladder cancer, as well as an association with increased CAF presence in the tumor microenvironment." (PMID 40141426, 2025). "Also, the release of CCL2, CXCL1, and Il-6 by CAAs is associated with bladder cancer cell migration." (PMID 40076892, 2025). "It is anticipated that by regulating the imbalance of IL-6 overproduction, there could be better treatment of bladder cancer-associated inflammation, thus IL-6 might serve as an important therapeutic molecule for bladder cancer." (PMID 41614883, 2025). "Furthermore, IL-6 from CAFs has also been linked to the induction of epithelial-mesenchymal transition, proliferation, migration, and invasion of bladder cancer cells." (PMID 38510850, 2024). "IL-6 and IL-1b are proinflammatory cytokines that have been linked to bladder cancer progression." (PMID 37901214, 2023). "IL-6 and IL-1β play a certain role in inflammatory stress caused by clinical infection and the immune regulation of patients and are known to possess positive clinical significance in the postoperative tissue trauma repair of bladder cancer." (PMID 35531475, 2022).